MMP9 (matrix metallopeptidase 9)
Diseases named in the same sentence as MMP9 in open-access papers (continued):
Sharing a sentence is not in itself a finding about the gene and the disease.
breast carcinoma (continued). "On the other hand, the expression of MMP-2 tended to be lower in breast carcinoma against that in normal tissues, with a fold change of -3.514, as suggested by in vitro studies, while MMP-2 and MMP-9 were highly expressed in breast cancer tissues and associated with worsening prognosis." (PMID 34181339, 2021). "Likewise, MMP-9 has been associated with tumor aggressiveness and/or poor prognostic in patients with breast cancer." (PMID 33114046, 2020). "In addition, another study showed that LA increased the expression and activity of MMP-9 in breast cancer cell lines, which was associated with increased migration of these cells." (PMID 32431615, 2020). "The increased metastatic potential of silenced Gal-3 breast cancer cells was found to be associated with an overall reduction in the tumor content of GAGs but enhanced chondroitin sulfate A and C, versican, and the matrix metalloproteinase 9 (MMP9) expressions." (PMID 31949431, 2019). "Recent clinical studies in cancer patients, have implicated that MMP-9 could be a strong and independent marker for aggressive breast cancer." (PMID 30925799, 2019). "Finally, the expression levels of the matrix metalloproteinase 9 (MMP9) were also evaluated since its expression is highly associated with a metastatic phenotype in breast cancer." (PMID 31949431, 2019). "In addition, fisetin treatment reversed 12-O-tetradecanoylphorbol-13-acetate (TPA) mediated cell migration in MCF-7 human breast cancer cells, which caused NF-κB inactivation and downregulation of MMP-9 expression." (PMID 31064104, 2019). "In this study, we identified that BMAL1 promoted the invasion and metastasis of breast cancer cells through regulating the expression of MMP9, and the possible underlying mechanism is mainly recruiting CBP to increase the acetylation level of p65, further activate the NF-κB signaling pathway." (PMID 31346317, 2019). "Importantly, serum samples from breast cancer patients have shown that high levels of MMP-2 and MMP-9 are directly associated with metastasis, and further provide evidence of the participation of these MMPs in breast cancer progression." (PMID 31671408, 2019). "In conclusion, our results indicate that changes in inflammatory biomarkers (plasma MMP9 and TNFα) associated with breast cancer risk and survival in breast cancer survivors with low plasma 25(OH)D levels, supplemented with vitamin D3 depends on VDR SNPs (Cdx2, TaqI and BsmI) and haplotypes." (PMID 31167402, 2019). "The newly discovered gene, TNFRSF12A, could be an important factor in explaining breast cancer progression associated with MMP-9." (PMID 30142200, 2018). "Similarly, a large meta-analysis, also from 2015, showed an association between TT genotype of MMP-9–1562 C/T polymorphism and a higher risk for breast cancer." (PMID 30352460, 2018). "Notably, our results, showing that high MMP-9 expression was associated with poor prognosis, were validated in a large-scale breast cancer cohort, METABRIC." (PMID 30142200, 2018). "High levels of TNFRSF12A associated with MMP-9 overexpression may be important to explain the progression of breast cancer, and survival could be improved using therapy targeting TNFRSF12A." (PMID 30142200, 2018). "Overall, our results revealed that the polymorphisms in the promoter region of MMP1, MMP3 and MMP9 when correlated with clinicopathological characteristics and survival rate have shown significant effects on the risk and progression of breast cancer, substantiated by in-silico analysis." (PMID 28961241, 2017). "In this study, we asked whether fibroblasts cooperate with breast cancer cells in tumor growth and vasculature, and whether this effect is linked to MMP9-driven vascularization." (PMID 28423685, 2017). "Interestingly, UDP release induces MMP-9 expression and enzyme activity in breast cancer cells through MAPK and NF-κB associated signaling pathways, which drive surrounding cancer cells to detach and escape from the primary site." (PMID 27074554, 2016).
breast carcinoma (continued). "In addition, it has also been reported in the breast cancer patients that there is a significant association between high MMP9 expression and poor survival." (PMID 26906973, 2016). "Cell motility is a critical process of invasion allowing primary tumors to metastasize, and invasion is principally stimulated by the gelatinase matrix-metalloproteinases (MMPs), and especially MMP-2 and MMP-9 were found to elevate in breast cancer and associated with disease progression." (PMID 27363023, 2016). "Our experiments with the MMP inhibitors Marimastat and SB-3CT showed for the first time that inhibition of MMP activities can reduce the expression of active integrin β1, suggesting an association between active MMP-2/MMP-9 and integrin β1 protein expression in metastatic breast cancer cells." (PMID 28721370, 2015). "Moreover, it has been reported that elevated expression of MMP-9 is positively associated with tumor invasion, metastasis, and poor prognosis in breast cancer." (PMID 26656588, 2015). "Taken together, our results suggested that expression status of TSP50/p65 as well as TSP50/MMP9 may be taken as a potential diagnostic, prognosis and therapeutic marker for human breast carcinoma in early stage." (PMID 25811800, 2015). "Finally, we investigated the expression and activity of extracellular cathepsin B, as this has been implicated in mediating invasive behavior of HER2-positive breast cancer cells, and activation of MMP-9 and infiltrative tumor cell growth in glioma." (PMID 25668816, 2015). "For example, expression of MMP-9 is relatively higher in the brain-seeking MDA-MB-231 breast cancer cell line variant compared to parental and bone-homing counterparts, and ectopic expression of MMP-2 in MDA-MB-231 cells increased the incidence of brain metastases after intracardiac injection." (PMID 25668816, 2015). "MMP-9 is known to degrade basement membranes in breast cancer, and several studies have also reported that MMP-9 may be associated with breast cancer initiation and progression through interactions between oncogenes and tumor suppressor genes." (PMID 25013462, 2014). "Increased levels of MMP-2 and MMP-9 have been previously associated with lung and breast cancers." (PMID 25025278, 2014). "Elevated tissue levels of MMP-9 are also associated with invasion, metastasis and poor prognosis in different types of cancer including cervical, colorectal, ovarian and breast cancer." (PMID 25151367, 2014). "MMP-9 in particular is considered to be one of the critical MMPs involved in cancer invasion and has been found to be directly associated with the invasion, metastasis, and poor prognosis of breast cancer." (PMID 24885456, 2014). "Because the expression of MMP-2 and MMP-9 has been implicated in the development and progression of many tumors, such as prostate, colorectal, breast cancer and cervical cancer, MMP2 has been deemed to be the most direct and important enzyme in invasion of cancer cells." (PMID 24885858, 2014). "Fascin and MMP-9 proteins are associated with parameters of poor prognosis in breast cancer." (PMID 24993803, 2014). "When stratifying by percent Native American ancestry, MMP3 and MMP9 were associated with breast cancer risk among women with more Native American ancestry only; the p for interaction with MMP9 remained statistically significant after adjustment for multiple comparisons (padj = 0.002)." (PMID 23696797, 2013). "Taken together, our results suggest that QSOX1 is a novel biomarker for risk of relapse and poor survival in Luminal B breast cancer, and has a pro-proliferative and pro-invasive role in malignant progression partly mediated through a decrease in MMP-9 functional activity." (PMID 23536962, 2013). "MMP-3 and MMP-9 are also implicated in the development of breast cancer brain metastases." (PMID 23344048, 2013). "In addition, aberrant overexpression of MMP-9 has been found to be associated with an increased invasive potential in breast cancer cells." (PMID 24130769, 2013).
breast carcinoma (continued). "in the present study, we investigated whether S100A7 overexpression could be mechanistically associated with the up-regulation of NF-κB, VEGF and MMP-9, resulting in the promotion of breast cancer cell invasion and growth, and vice versa." (PMID 23618129, 2013). "However, we observed few differences in breast cancer risk by Native American ancestry, with only MMP9 being different by ancestry group." (PMID 23696797, 2013). "In addition, it is worthwhile to investigate if surgical treatment of tumor results in subsequent clearing of both markers in serum assuming that the second primary cancer or recurrent breast cancer is causative for the elevated lipocalin-2 and MMP-9." (PMID 22640376, 2012). "Epidemiological evidence suggests an association between inflammation and breast cancer and several studies investigating the role for MMPs, ADAMs and TIMPs in breast cancer risk and progression have demonstrated that high levels of MMP9 are associated with poor breast cancer prognosis." (PMID 22276018, 2009). "Additionally, KP1019 clearly reduces the release of metalloproteases of the extracellular matrix (MMP-2 and MMP-9), enzymes often associated with unfavourable prognosis in many cancers including mammary tumours." (PMID 19789639, 2009). "Similarly, inhibition of MMP9 production in tumour-associated macrophages by a hypomorphic Ets-2 mutation also inhibited tumour development in the PyMT mouse model of breast cancer." (PMID 15164120, 2004). "The activity of MMP-2 and MMP-9 in serum or plasma, measured by gelatine zymography, has been shown to distinguish between breast cancer subclassification and various risk factors, predict lymph node metastasis, and evaluate treatment response in breast cancer patients." (PMID 38956273, 2024). "CPEB1 absence in breast cancer not only leads to the loss of polarity of mammary epithelial cells but also lengthens poly(A) and increases the polyadenylation and translation efficiency of MMP9 mRNA (tumor metastasis-promoting factor), which promotes the metastasis of breast cancer." (PMID 36052258, 2022). "Moreover, increased NF-κB activity was observed in S100A7-overexpressing breast cancer cells, associated with evaluated levels of NF-κB target genes matrix metalloproteinase 9 (MMP9) and vascular endothelial growth factor (VEGF), resulting in proliferation and invasion." (PMID 32722137, 2020). "This study aims to assess the prognostic value of MMP9 and its association with cytoskeletal modulators in early-stage invasive breast cancer (BC)." (PMID 32445177, 2020). "In contrast, LEF1 was able to regulate MMP-7 expression and activity in breast cancer cells, whereas another previous study showed that circulating MMP-2 and MMP-9 could be used to potentially classify patients into low risk, high risk, benign disease, and breast cancer." (PMID 24098538, 2013). "Indeed, breast cancer-associated fibroblasts, in contrast to those found in normal breast tissue, overexpress heregulin; presence of this ligand promotes MMP9 expression and secretion in breast cancer and is likely to enhance the cells’ invasive capacity in vivo." (PMID 23039365, 2012). "Interestingly, in early breast cancer, elevated MMP-9 associates with better prognosis." (PMID 23216739, 2012). "Among the key genes found in these enriched categories, TPSD1, FABP4, CARTPT, TRH, CSN3, and MMP9 stand out based on previously published data, which suggest their critical roles in cancer progression, including breast cancer." (PMID 40870889, 2025). "Rezaei and colleagues demonstrated that the expression levels of MMP-2 and MMP-9 were suppressed in minocycline-treated MCF-7 breast cancer cells." (PMID 40471394, 2025). "Several studies have substantiated MMP-9's involvement in catalyzing both the onset and metastasis across a spectrum of cancers, including gastric cancer 92, breast cancer 93, 94, colon cancer 95, lung cancer 96, 97, among others." (PMID 40365275, 2025).
breast carcinoma (continued). "This cross-sectional study aimed to explore the fibrinolysis components values and MMP-9 levels in a specific population of patients with early breast cancer and metastatic breast cancer in Tucumán, Argentina." (PMID 40266038, 2025). "Combined analyses indicated that ARD1‐positive/MMP‐9‐negative patients exhibited the best OS and DFS, and multifactorial analysis confirmed the significant impact of ARD1 and MMP‐9 expression on breast cancer prognosis." (PMID 40026288, 2025). "In some biological settings, E2 is profibrotic; for instance, in dermal fibroblasts, E2 promotes fibrosis by inducing TGF-β1 and TGF-β2 expression, and in breast cancer cells, E2 increases syndecan-2 and MMP-9 expression through ERα signaling." (PMID 41533935, 2025). "Previous studies established that dieckol, a major component, inhibits the proliferation and invasion of MCF-7 breast cancer cells by suppressing MMP9 expression through the inhibition of PI3K/Akt, Wnt/β-catenin, and NF-κB signaling." (PMID 41590709, 2025). "ETS1 and MMP-1 are co-expressed in skin angiosarcoma, whereas ETS1 is co-expressed with MMP-1 and MMP-9 in ovarian carcinoma cells and in stromal fibroblasts of breast carcinoma." (PMID 39941022, 2025). "This cross-sectional study aimed to explore the standard coagulation tests, t-PA, PAI-1, DD, and MMP-9, in a population from Tucumán, Argentina, including individuals with benign breast pathologies, early-stage breast cancer, and metastatic breast cancer." (PMID 40266038, 2025). "Among them, the gelatinases MMP-2 and MMP-9 have been widely studied as potential biomarkers in breast cancer, with their overexpression consistently correlated with poor outcomes in several types of cancer." (PMID 40943584, 2025). "It decreases the metastasis-related proteins (Vimentin, MMP-9, and E-cadherin) in breast cancer (MDA-MB-231) and lung cancer (A549) cells." (PMID 40490812, 2025). "Macrophage membrane-camouflaged hollow bismuth selenide nanoparticles loaded with quercetin downregulated Akt phosphorylation and MMP-9 expression, inhibiting breast cancer metastasis." (PMID 40284474, 2025). "Suppression of MMP‐9 has been shown to reduce the migration and invasion ability of breast cancer cells." (PMID 39980332, 2025). "Other studies have also shown that P2X7R activation increases the expression level of E-cadherin and MMP-9, and promotes the migration and invasion of breast cancer cells." (PMID 40265472, 2025). "At a concentration of 4 mg/mL (PLE PI), 2 mg/mL (HIFU PI), and 2.4 mg/mL (hydrolysates), all treatments significantly reduced breast cancer cell migration and metalloproteinase 9 (MMP-9) activity (active and pro form), and enhanced cell adhesion." (PMID 40966212, 2025). "MMP2 and MMP9, which catalyze the breakdown of gelatin IV, the primary component of the extracellular matrix, are the most common MMPs found in breast cancer." (PMID 40735254, 2025). "When these findings are combined with the primary outcome of our mathematical model, MMP2 and MMP9 emerge as potential therapeutic targets for combating breast cancer." (PMID 40259907, 2025). "PAI-1 and MMP-9 levels were higher in patient with early breast cancer than those with benign disease." (PMID 40266038, 2025). "MMP-9 activity in the choroid plexus cells also resulted in the release of Tau from breast cancer cells, which formed neurofibrillary tangles that further destabilized the BCSFB." (PMID 40076927, 2025). "LRRN1 overexpression consistently downregulated the protein expression of focal adhesion kinase (FAK), matrix metalloproteinase-2 (MMP2), and matrix metalloproteinase-9 (MMP9) in both breast cancer cellines." (PMID 41458604, 2025). "Several studies found that the inhibition of MMP-2 and MMP-9 can reduce breast cancer angiogenesis and metastasis." (PMID 40176865, 2025). "Several studies found that overexpression of MMP-2 and MMP-9 correlated with breast cancer metastasis and poor prognosis." (PMID 40176865, 2025).
breast carcinoma (continued). "It is still unclear as to why the expression levels of MMP-2 and MMP-9 in HS578T-Hyg breast cancer cells and M13HS-2 and − 8 tumor hybrids remained unaltered or only moderately decreased." (PMID 40471394, 2025). "MMP-9 also serves as a biomarker for various diseases, such as in the detection of breast cancer, where it is found to be present in the urine of breast cancer patients." (PMID 41002342, 2025). "Further, they also restricted breast cancer metastasis to the distant organs due to the antioxidant activity as evidenced by the down-regulation of MMP-9 and other inflammatory markers, respectively." (PMID 40677396, 2025). "In a murine xenograft model, overexpression of LCN2 in the MCF-7 human breast cancer cell line increased MMP9 levels, which was accompanied by increased proliferation and angiogenesis." (PMID 40109857, 2025). "This is further supported by the study of Rezaei and colleagues, which demonstrated that minocycline significantly reduced the expression of MMP-2 and MMP-9 as well as the migratory activity of MCF-7 breast cancer cells." (PMID 40471394, 2025). "MMP‐9 has been shown to correlate with poor survival and a short recurrence‐free period of breast cancer patients." (PMID 39980332, 2025). "In our research, we revealed that GATA4 inhibits the invasion and migration of breast cancer cells by downregulating MMP9 expression." (PMID 38653973, 2024). "At the same time, M0 macrophages stimulated by MCF-7 exosomes upregulate the expression of MMP2 and MMP9 by activating ERK signaling in MCF-7 breast cancer cells, thereby promoting the proliferation and migration of tumor cells." (PMID 38356723, 2024). "Utilizing the MDA-MB-231 breast cancer cell model, we demonstrate that the cooperative action of these cytokines significantly enhances MMP-9 expression through a previously unappreciated mechanism involving H3K36 dimethylation." (PMID 39351229, 2024). "In breast cancer lung metastasis, MMP-9 disrupts VE-calmodulin junctions in the extracellular matrix of the pulmonary vascular endothelium, promoting tumour cell extravasation and metastatic nodule formation." (PMID 39156102, 2024). "Another study demonstrated that arctigenin exhibits anti-metastatic effects on breast cancer cell lines by inhibiting MMP-9 and uPA by targeting the Akt, NF-κB, and MAPK signaling pathways." (PMID 39717276, 2024). "Altogether, these results demonstrate that TGF-β priming amplifies the TNF-α-mediated induction of MMP-9 in breast cancer cells." (PMID 39351229, 2024). "The inhibition of STAT3 phosphorylation has reduced the expression of matrix metallopeptidases MMP2 and MMP9, which help enable breast cancer invasion and metastasis." (PMID 38935814, 2024). "The expression of MMP-2 and MMP-9 is increased in many types of cancer, including lung cancer, breast cancer and glioma, and cervical cancer and is considered an important prognostic factor." (PMID 39274874, 2024). "Our research asserted that GATA4 mitigates breast cancer cell metastasis through the downregulation of MMP9 transcription." (PMID 38653973, 2024). "Sen and Chatterjee (2011) showed that EGCG downregulates EGF-induced matrix metalloproteinase-9 (MMP9) in ER+ breast cancer cells, thereby shutting down cell invasion and metastasis." (PMID 38543147, 2024). "The upregulation of MMP‐9 through the activation of AP‐1 and NF‐κB is facilitated by MT‐2A, thereby promoting the invasion and migration of breast cancer cells." (PMID 39676279, 2024). "By using LOX-RNAi-LV to transduce the MDA-MB-231 breast cancer cell line, researchers have observed a significant inhibition in the expression of MMP-2 and MMP-9, leading to reduced invasion and migration abilities of breast cancer cells." (PMID 39247609, 2024). "Our in vitro data show that TNF-α and TGF-β cooperatively upregulate MMP-9 expression in breast cancer cells." (PMID 39351229, 2024).